MMP9 (matrix metallopeptidase 9)
Diseases named in the same sentence as MMP9 in open-access papers (continued):
Sharing a sentence is not in itself a finding about the gene and the disease.
osteosarcoma (continued). "Previous study reported that IL-17A and IL-17R interaction enhanced the metastasis of osteosarcoma cells via the expression of VEGF, MMP-9 and CXCR4." (PMID 26850593, 2016). "Nobiletin inhibits osteosarcoma cell metastasis by suppressing the expression and binding activities of NF-κB and CREB on MMP-2 and MMP-9 promoters." (PMID 27144433, 2016). "In conclusion, we have shown that glucosamine sulfate exerts a pronounced suppressive effect on MMPs in osteosarcoma cell lines in vitro; this effect was most pronounced for MMP-3 and MMP-9 to a lesser extent." (PMID 27562075, 2016). "Proliferation, migration, cell cycle analysis and expression in osteosarcoma cell lines of matrix metalloproteinases such as gelatinases MMP-2 and MMP-9 and their inhibitors TIMP-1 and TIMP-2 were studied." (PMID 26959001, 2016). "Sensitivity to doxycycline and EGCG in normal osteosarcoma U2OS cells was nearly equivalent in MMP-2 secretion, but secretion of MMP-9 was significantly more sensitive to doxycycline than EGCG." (PMID 24190483, 2014). "Osteosarcoma and rhabdomyosarcoma showed bands corresponding to MMP-2 and -9 with dose-dependent enhancement of MMP-9 with phorbol 12-myristate 13-acetate (PMA) treatment." (PMID 24190483, 2014). ", a traditional medicinal plant, possesses antimetastatic effects on human osteosarcoma cells by decreasing MMP-2 and MMP-9 secretions through p38 and Akt signaling pathways." (PMID 24278338, 2013). "On gelatinase zymography, osteosarcoma MNNG-HOS showed a band corresponding to MMP-2 and induction of MMP-9 with PMA (100 ng/ml) treatment." (PMID 23900236, 2013). "Osteosarcoma xenografts express high levels of VEGF-A, angiopoetin 1, Tissue Factor and MMP9, relative to leukemia xenografts." (PMID 22530037, 2012). "There was a significant correlation between the expression of MMP-9 and pre-ALP in these osteosarcoma samples." (PMID 22333159, 2012). "In the present study, the MMP-inhibitor Marimastat significantly inhibited osteosarcoma cell invasion, which suggest that MMPs are vital factor in osteosarcoma invasion, and that risedronate suppressed the expressions of MMP-2 and MMP-9." (PMID 19624845, 2009). "In the present study, we found that risedronate suppresses cell invasion and the gelatinolytic activities and protein and mRNA expressions of MMP-2 and MMP-9 in the SaOS-2 and U2OS osteosarcoma cell lines." (PMID 19624845, 2009). "Studies have shown that in the osteosarcoma cell line U20S, the activation of the NF-κB signaling pathway can up-regulate key metastasis-promoting factors such as vascular endothelial growth factor (VEGF), MMP2 and MMP9." (PMID 40786506, 2025). "In osteosarcoma, KRAS inhibition decreased MMP1, MMP9, and AKT/ETS1 signaling." (PMID 40779492, 2025). "Conversely, the overexpression of PDGFD, in either non-metastatic osteosarcoma or metastatic osteosarcoma, resulted in a decrease in MMP9, β-catenin, and ZEB expression, while E-cadherin expression was increased." (PMID 38652223, 2024). "Furthermore, the upregulation of matrix metallopeptidase genes, including MMP1, MMP2, MMP9, MMP11, and MMP16, has been observed in osteosarcoma (OS)." (PMID 38966281, 2024). "Their findings indicated that ERK5 expression stimulates MMP-9 expression and regulates the invasion of osteosarcoma cells; however, silencing ERK5 does not impact cell proliferation." (PMID 38785963, 2024). "One study demonstrated that knocking down UBCH10 in osteosarcoma cell lines resulted in the downregulation of Ki-67, MMP-3 (matrix metalloproteinase-3), and MMP-9 (matrix metalloproteinase-9), leading to decreased proliferation, invasion, and migration capabilities of OS cells." (PMID 39062505, 2024).
osteosarcoma (continued). "Mechanical stresses from the microenvironment have been reported to regulate the PI3K/Akt signaling pathway (the most activated downstream effectors in the oncogenic landscape), promoting the expression of MMP-2 and MMP-9, thus degrading ECM and enabling osteosarcoma cell invasion and metastasis." (PMID 37175397, 2023). "The antimetastatic effect of aprepitant in osteosarcoma is probably attributed to its ability to modulate the transcriptional regulator nuclear factor kappa B (NF-κB) and, subsequently, its target genes, including MMP-2, MMP-9, and VEGF-A." (PMID 36983138, 2023). "Proliferation, invasion, and migration abilities of osteosarcoma cells and the level of protein expression of p-PI3K, p-Akt, MMP2, and MMP9 were significantly decreased with enhanced miR-652 expression (P < 0.01), while overexpression of HOXA9 reversed this situation." (PMID 35111226, 2022). "There are some studies on the relationship between MMP9, VWF, and osteosarcoma." (PMID 35814015, 2022). "Furthermore, lnc-KASRT overexpression increased KLF6-SV1, MMP1, and MMP9 expression and decreased SRSF1 and KLF6-WT expression in osteosarcoma mice, but lnc-KASRT downregulation showed the opposite trend." (PMID 34568030, 2021). "Additionally, in osteosarcoma cells, it also possesses the anti-metastatic activity by down-regulating the MMP-2 and MMP-9 secretions and increasing the TIMP-1 and TIMP-2 expressions via Akt-dependent and p38 pathways." (PMID 34068885, 2021). "Furthermore, osteosarcoma-derived EVs’ treatment of fibroblasts also resulted in enhanced MMP2 and MMP9 activity as well as increased fibronectin expression." (PMID 32751693, 2020). "Additionally, MMP-2, MMP-9, and MMP-13 overexpression has been revealed to be a promising indicator for osteosarcoma prognosis and pulmonary metastasis." (PMID 33228783, 2020). "Therefore, we measured the expression of N‐cadherin, MMP‐9 and MMP‐2 in osteosarcoma cells after BD stimulation." (PMID 31631559, 2019). "Numerous metastasis-related genes were regulated by PC4, however, MMP9 did not seem to be the sole gene account for osteosarcoma lung metastasis." (PMID 28881805, 2017). "In osteosarcoma patients, MMP-2 and MMP-9 are generally overexpressed." (PMID 29340064, 2017). "In this context, it has been demonstrated that high PC4 expression in osteosarcoma correlates with poor prognosis, and suppression of PC4 blocked the pulmonary metastasis by reducing malignancy phenotype through transcriptional level depression of MMP9." (PMID 28881805, 2017). "In addition, we showed that baicalein suppressed osteosarcoma cells adhesion, migration, and invasion by decreasing the expression and activity of MMP-2 and MMP-9." (PMID 29156780, 2017). "In this context, upregulation of MMP9 but not MMP2 has been shown to contribute to increased metastatic ability of osteosarcoma cells." (PMID 26979530, 2016). "Further, analysis of osteosarcoma cells isolated from 23 pretreatment tumor tissues showed high MMP2 levels in all samples, while MMP9 could only be detected in one sample." (PMID 26979530, 2016). "In contrast to MMP9, several studies observed a more important role of MMP2 in osteosarcoma." (PMID 26979530, 2016). "Strong overall MMP activities could be detected in osteosarcoma pretreatment biopsies with MMP2 and MMP9 as predominant active MMPs." (PMID 26979530, 2016). "Growth and development of osteosarcoma depends mainly on the activation of VEGF165, MMP2 and MMP9." (PMID 26109911, 2015). "Interestingly, a previous report indicated that all osteosarcoma cells from tissue specimens and established cell lines were found to express MMP-2, but pro-MMP-9 was detected in only one tissue sample and one cell line (U-2OS)." (PMID 25605016, 2015). "For example, increased expression of MMP-9 has been found to correlate with osteosarcoma metastasis in patients and inhibitors of MMPs, such as TIMP-1 have been shown to inhibit invasiveness of osteosarcoma tumor cells in vitro." (PMID 24190483, 2014).
osteosarcoma (continued). "U-2OS osteosarcoma cells showed strong bands corresponding to inactive MMP-2 and MMP-9 and faint bands corresponding to active MMP-2 and MMP-9 dimer; PMA treatment enhanced MMP-9 and MMP-9 dimer activity." (PMID 23900236, 2013). "As expected, a significant positive correlation was found between the secretion of u-PA and MMP-2/MMP-9 and a significant negative correlation between u-PA and TIMP-2 and between MMP-2/MMP-9 and TIMP-2 secretion by NM treatment of osteosarcoma and rhabdomyosarcoma cells." (PMID 23900236, 2013). "the downregulation of PDGFD, regardless of non-metastatic osteosarcoma or metastatic osteosarcoma, led to a significant upregulation of matrix metallopeptidase 9(MMP9), β-catenin, and zinc finger E-box binding homeobox (ZEB) expression, while E-cadherin expression was downregulated." (PMID 38652223, 2024). "However, whether FBXO22 affects the proliferation and motility of osteosarcoma cells by targeting FoxO1 and other proteins, such as p57, PTEN and MMP‐9, is elusive." (PMID 39153212, 2024). "Similar results have been obtained in osteosarcoma cells, where TGF-β signaling induces a switch in the E-cadherin/N-cadherin cell profile as well as an increase in vimentin, whereas melatonin appears to reverse this effect through the inhibition of Snail, MMP-9 and HIF-1α." (PMID 38473317, 2024). "CCN1 induces MMP-2, MMP-9, MMP-14 and TIMP-3, mediates prometastatic effects via the IGF-1/IGF1Rβ pathway, and is elevated in MG63 M7 and M10 sublines selected in vivo for a migratory phenotype; in addition, its inhibition decreases lung-metastatic potential of osteosarcoma cell lines in vivo." (PMID 34228239, 2021). "Thus, inhibition of GSK-3β may suppresses osteosarcoma cell migration and invasion by reducing the expressions of MMP-2 and MMP-9." (PMID 33969873, 2021). "Therefore, it could be speculated that GSK-3β might promote the osteosarcoma metastasis by reducing the stability of PTEN and increasing the phosphorylation of FAK, and then accelerate the secretions of MMP-2 and MMP-9." (PMID 33969873, 2021). "However, the prognostic value of serum MMP-9 levels for metastases in patients suffering from osteosarcoma was found to be statistically non-significant." (PMID 32377334, 2020). "There were a small number of recent studies reporting prognostic biomarkers for osteosarcoma which were associated with lung metastases and survival such as PLA2G16, MMP-2, CXCR4 and MMP9, but none of them showed correlation with response to chemotherapy treatment." (PMID 28846700, 2017). "Moreover, nobiletin effectively suppressed SP-1 and CREB expressions, these findings are consistent with those in reports on leukemia cells, cholangiocarcinoma cells and osteosarcoma cells, implicating the importance of NF-κB and CREB in the regulation of MMP-2 and MMP-9 in U2OS and HOS." (PMID 27144433, 2016). "However, IL-32 did not affect MMP-2 and MMP-9 expression in osteosarcoma cells whereas MMP-13 is involved in the IL-32-induced migration, suggesting that different types of proteases affects the migratory processes in a cell-type specific manner." (PMID 27589563, 2016). "Therefore, other factors, such as matrix metalloproteinase-9 (MMP-9), MMP-2, and vascular endothelial growth factor, may also be involved in promoting the proliferation and invasion of osteosarcoma cells." (PMID 25890096, 2015). "Therefore, given the known importance of MMP-2 and MMP-9 in tumor invasion, our findings suggest that the inhibitory effect of risedronate on osteosarcoma cell invasion is probably due to MMP inhibition rather than tumor cell death." (PMID 19624845, 2009). "Moreover, the up-regulation of MMP-9, Vimentin and N-cadherin and the downregulation of E-cadherin were observed in Lnc-ZFAS1 overexpressed U2OS cells, and the contrast results were induced by Lnc-ZFAS1 depletion, implying Lnc-ZFAS1’ promotion effect on EMT in osteosarcoma." (PMID 36473367, 2023).
osteosarcoma (continued). "Besides, the application of MMP9 inhibitor regarding osteosarcoma had not been reported so far, so further research in this field could make a remarkable significance in the chemotherapy of osteosarcoma." (PMID 34261456, 2021). "The following study confirmed our hypothesis, we demonstrated that PC4 shRNA downregulated MMP9 mainly through SP1 at the transcriptional level by forming the SP1 transcriptional complex, and this may contribute mechanistically to lung metastases in osteosarcoma." (PMID 28881805, 2017). "Furthermore, MMP9 activity and gene expression has been reported to correlate with the metastatic potential of rat osteosarcoma, while MMP2 could not be detected." (PMID 26979530, 2016).
Hypertension (174 papers, 2008 to 2026). The presence of chronic increased pressure in the systemic arterial system. "It is interesting to see that the MMP-9-1562C/T polymorphism increased the risk of nephrolithiasis in patients with hypertension." (PMID 37332754, 2023). "MMP-2 and MMP-9 both have pro- and anti-inflammatory effects and, specifically, MMP-9 has been associated with increased arterial stiffness and elevated blood pressure in hypertension." (PMID 35742125, 2022). "Several isoforms of NOX have been reported to participate in MMP-9 upregulation associated with numerous diseases, such as cancer, ischemic injury, and hypertension." (PMID 35054789, 2022). "Vasoactive factors are released by increasing MMP2 and MMP9, which further increases the risk of hypertension during late gestation." (PMID 36910123, 2022). "The rs17567 MMP-9 (R279Q) polymorphism was evaluated in association with carotid artery stenosis and hypertension." (PMID 35449607, 2022). "Although the association between MMP-9 levels and hypertension was detected in several studies, the mechanism underlying this effect was not investigated." (PMID 34625635, 2021). "While most studies have implicated MMP-2 as a major cause of vascular dysfunction in hypertension, MMP-9 is apparently also involved." (PMID 33923477, 2021). "In fact, the exaggerated activation of MMP-9 has been associated with an abnormal glomerular basement membrane structure and consequent albuminuria escape in treated hypertension." (PMID 32225016, 2020). "In this context, there is evidence that MMP-9 plays an important role in structural alterations associated with hypertension and its complications." (PMID 32164582, 2020). "MMP-9 was significantly associated with high blood pressure [beta: 2.9 (0.4–5.4), low HDL [-2.5 (-5.0–0.0), triglycerides (best 3.7 (1.4–6.1) and overall cardiovascular risk [4.7 (2.6–6.8) after adjusting for age, and sex8." (PMID 32246106, 2020). "By analyzing the hypertension-free survival, we found that OSAS severity, lowest sleeping SpO2, and serum MMP-9 were all risk factors for hypertension onset." (PMID 29693002, 2018). "In an animal study, MMP-9-deficient mice phenocopied PE symptoms of human patients such as intrauterine growth restriction and hypertension." (PMID 28143958, 2017). "Two other genes associated with response to oxidative stress (Clu and Mmp9) are known as genes related to hypertension and kidney diseases." (PMID 26821914, 2016). "The reduced concentration of MMP-9 in hypertension is associated with a decrease in the total activity of MMP-9, resulting in the accumulation of collagen in vascular wall of resistive arteries, reduction in their elasticity, and progression of hypertension." (PMID 27490532, 2016). "Although in the younger male group, TIMP1 rs4898 variant was associated with hypertension risk and MMP9 rs3787268 variant had a borderline protection from DM risk, none of them were associated with SDICH risks in the young males." (PMID 25932641, 2015). "MMP-9 has also been shown to be elevated in patients with acute coronary syndrome and MMP-9 and −12 have been pharmacogenetically associated with hypertension." (PMID 23805173, 2013). "The available data also show a possible association of MMP9 with the pathogenesis and treatment of hypertensive disease." (PMID 20037727, 2009). "The association of CXCL1 increase to the inflammatory activation of rat vascular SMC induced by hypertension, to the causes of hypertension and MMP9 release in human diseases, and to AAA growth support the potential relevance of Lad effects over CXCL1 in the perspective of AAA therapy." (PMID 41227357, 2025). "Particularly MMP-2 and MMP-9 have been linked to the development of hypertension." (PMID 35774422, 2022). "MMP-9 levels are thought to enhance inflammation and vascular wall degradation, resulting in greater arterial stiffness and a potentially increased risk of hypertension and other CVD." (PMID 36555898, 2022).